RPL14P1 (ribosomal protein L14 pseudogene 1)
Synonyms: bcm1298; RPL14L; RPL14_1_1246
Gene: Processed pseudogene on chromosome 12 (62,965,325 to 62,965,969, forward strand). Ensembl gene ENSG00000139239.
Diseases named in the same sentence as RPL14P1 in open-access papers:
RPL14P1 is named in the same sentence as 1 disease in open-access papers, as found by Europe PMC text mining. Sharing a sentence is not in itself a finding about the gene and the disease.
RPL14P1 shares sentences with these, for which no sentence is quoted: breast carcinoma (1 paper).